RBPMS2 (RNA binding protein, mRNA processing factor 2)
Description:
RNA-binding protein involved in the regulation of smooth muscle cell differentiation and proliferation in the gastrointestinal system. Binds NOG mRNA, the major inhibitor of the bone morphogenetic protein (BMP) pathway. Mediates an increase of NOG mRNA levels, thereby contributing to the negative regulation of BMP signaling pathway and promoting reversible dedifferentiation and proliferation of smooth muscle cells (By similarity). Acts as a pre-mRNA alternative splicing regulator (By similarity). Mediates ACTN1 and FLNB alternative splicing (By similarity). Likely binds to mRNA tandem CAC trinucleotide or CA dinucleotide motifs.
Tractability: PROTAC: ubiquitination databases record sites on it; its protein half-life has been measured.
Gene: Protein-coding gene on chromosome 15 (64,739,886 to 64,775,621, reverse strand). Ensembl gene ENSG00000166831.
Subcellular location: Cytoplasm; Nucleus; Cytoplasm, Stress granule
Gene Ontology:
Molecular function: identical protein binding; mRNA binding; protein binding; protein homodimerization activity; nucleic acid binding; RNA binding
Biological process: negative regulation of smooth muscle cell differentiation; embryonic digestive tract morphogenesis; negative regulation of BMP signaling pathway; positive regulation of smooth muscle cell proliferation; regulation of alternative mRNA splicing, via spliceosome
Cellular component: cytoplasm; cytoplasmic stress granule; cytosol; nucleus
Genetic constraint (gnomAD): Loss-of-function variants: 14 observed, 22.91 expected, observed/expected ratio (o/e) 0.61, 90% interval 0.4 to 0.95. The upper end of that interval is the gene's LOEUF score, 0.95, which puts it in group 4 of 6, group 1 being the genes least tolerant of losing a copy. Missense variants: 252 observed, 259.23 expected, observed/expected ratio (o/e) 0.97, 90% interval 0.88 to 1.08. Synonymous variants: 127 observed, 104.98 expected, observed/expected ratio (o/e) 1.21, 90% interval 1.05 to 1.4.
Homologues: Orthologues: chimpanzee RBPMS2 (99% identical), macaque RBPMS2 (97% identical), dog RBPMS2 (95% identical), pig RBPMS2 (92% identical), rat Rbpms2 (91% identical), mouse Rbpms2 (89% identical), rabbit RBPMS2 (85% identical), zebrafish rbpms2a (80% identical), zebrafish rbpms2b (77% identical), guinea pig RBPMS2 (76% identical), Caenorhabditis elegans mec-8 (42% identical). Paralogues in human: RBPMS (65% identical).
Diseases named in the same sentence as RBPMS2 in open-access papers:
RBPMS2 is named in the same sentence as 13 diseases in open-access papers, as found by Europe PMC text mining. Sharing a sentence is not in itself a finding about the gene and the disease. The quoted sentences say what the papers report.
gastric cancer (4 papers, 2018 to 2025). A primary or metastatic malignant neoplasm involving the stomach. "In gastric cancer, RBPMS2 is overexpressed, predicts poor prognosis, and promotes proliferation, invasion, and migration by suppressing NLRP3/caspase-1/GSDMD-mediated pyroptosis." (PMID 41562091, 2025). "It has been reported that MIR100HG has been used as proto-oncogene and RBPMS2 is used as a target for gastric cancer markers and cancer targeted therapy." (PMID 29301256, 2018). "The results showed that DAZ1, WIPF3, RBPMS2, and NOVA1 were low expressed in gastric cancer (P<0.05), and KIAA0101 and COL5A2 were highly expressed (P<0.05)." (PMID 34234866, 2021).
idiopathic pulmonary arterial hypertension (1 paper, 2025). A sporadic form of pulmonary arterial hypertension (PAH) characterized by elevated pulmonary arterial resistance leading to right heart failure. "Hemoglobin subunit gamma-2 (HBG2) was reported in association with high-altitude pulmonary hypertension (HAPH), while RNA-binding protein with multiple splicing 2 (RBPMS2) was identified as a potential biomarker and therapeutic target in idiopathic pulmonary arterial hypertension." (PMID 40963580, 2025).
pancreatic cancer (1 paper, 2021). "However, the increased expression of RBPMS2 has been correlated with favorable clinical outcomes in pancreatic cancer, which was similar to our data." (PMID 34001012, 2021).
cancer (6 papers, 2018 to 2026). A tumor composed of atypical neoplastic, often pleomorphic cells that invade other tissues. "At the level of individual genes, the most significant decrease in expression was observed for RBPMS2 (log2FC = −3.11), which normally participates in the development and dedifferentiation of digestive smooth muscle cells, but has also been affiliated with the progression of several types of cancer." (PMID 36829477, 2023). "According to the regulation efficacy data, the positive regulation of TRIM15 and NHERF1 by CREB1 was reversed from normal to cancer; the negative regulations of TCEAL2, RBPMS2 and FAM20C by CREB1 disappeared; and the negative regulation of FERMT2 was reversed from normal to cancer." (PMID 35421923, 2022).
tumor (5 papers, 2021 to 2025). "Further, the investigated proteins showed significant associations between Noggin and RBPMS2 proteins in the invasive front as well as the tumor center (P < 0.001)." (PMID 34001012, 2021). "In addition, level of DNA methylation of RBPMS2 in GC tissues was increased and DNA methylation of RBPMS2 was strongly associated with tumor invasion, Borrmann classification and TNM stage." (PMID 35137653, 2022). "Overall, we demonstrated that RBPMS2 DNA methylation can inhibit tumor progression, suggesting that RBPMS2 DNA methylation functioned as a potential candidate for the diagnosis of GC." (PMID 35137653, 2022). "The Western blot and IHC tests showed that RBPMS2 expression was prominently reduced in GC tissues compared to non-tumor paracarcinoma specimens." (PMID 35137653, 2022). "In our study, MSP results indicated that RBPMS2 promoter region was extra methylated in GC tissues compared to the adjacent non-tumor specimens." (PMID 35137653, 2022). "DNA methylation inhibitors 5-aza-DC and RG108 reversed the function of suppressing RBPMS2 in GC cell malignant behaviors, implying that DNA methylation of RBPMS2 leads to the downregulation of RBPMS2 in GC, and thereby promoted tumor progression." (PMID 35137653, 2022). "Further analysis showed that RBPMS2 DNA methylation was related to the depth of tumor invasion, Borrmann classification, and TNM stage." (PMID 35137653, 2022). "In the present study, the results elucidated that DNA methylation of RBPMS2 was responsible for its downregulation in GC and promoted tumor progression, suggesting that DNA methylation of RBPMS2 was essential for the diagnosis of GC." (PMID 35137653, 2022). "In the current study, we also demonstrated that RBPMS2 DNA methylation was related to the depth of tumor invasion, Borrmann classification and TNM stage, suggesting that DNA methylation of RBPMS2 was a promising molecular diagnostic biomarker of GC." (PMID 35137653, 2022). "Collectively, these data implied that DNA methylation inhibitor, 5-aza-DC, partially counterbalanced the function of suppressing RBPMS2 on tumor growth in vivo." (PMID 35137653, 2022). "MSP results indicated that the DNA methylation expression of RBPMS2 promoter was significantly enhanced in GC tissues in relation to non-tumor specimens." (PMID 35137653, 2022). "The expression of Noggin and RBPMS2 proteins in tumor cells at the tumor center and invasive front of resected GC was evaluated by immunohistochemistry, and in conjunction with clinicopathological parameters the patient survival was analyzed." (PMID 34001012, 2021). "RBPMS2 protein expression was high at the tumor center (n = 86, 52.8%) and low at the invasive front (n = 69, 42.3%), while Noggin protein expression was high in both tumor center (n = 91, 55.8%) and the invasive front (n = 90, 55.2%)." (PMID 34001012, 2021). "The prognostic value of stroma-related proteins, Noggin and RBPMS2, expressed in the tumor center or invasive front, is complex and debatable." (PMID 34001012, 2021). "Univariate and multivariate regression analysis for tumor progression showed that expression of RBPMS2 and DSC3 were found to be independent prognostic biomarkers in progressive and de novo MIBC groups, respectively." (PMID 33731721, 2021). "Among 31 cases with the discrepant expression of RBPMS2 between the tumor center and invasive front, high RBPMS2 expression in the tumor center and low in the invasive front accounted for 24 (77.4%) cases." (PMID 34001012, 2021). "Progressive and de novo MIBC groups present different prognostic biomarkers for tumor progression (RBPMS2 in progressive MIBC and DSC3 in de novo MIBC) and for CSS (CALD1 in progressive MIBC and LCOR in de novo MIBC)." (PMID 33731721, 2021). "To sum, our data demonstrated that DNA methylation of RBPMS2 was responsible for its downregulation in GC and promoted tumor progression, indicating DNA methylation of RBPMS2 might serve as a valuable potential parameter in GC pathogenesis." (PMID 35137653, 2022).
tumor (continued). "On contrast, the function of RBPMS2 on proliferation and apoptosis of tumor cells could be counteracted in part by treatment with 5-aza-DC." (PMID 35137653, 2022). "In addition, we found that RBPMS2 DNA methylation was related to the depth of tumor invasion, Borrmann classification, and TNM stage." (PMID 35137653, 2022). "We also evaluated the role of RBPMS2 DNA methylation in GC tumor growth invivo." (PMID 35137653, 2022). "However, the high expression of RBPMS2 in tumor center (n = 86, 52.8%) was more frequent than in the invasive front (n = 69, 42.3%)." (PMID 34001012, 2021). "Therefore, we evaluated the expression of Noggin and RBPMS2 proteins in the tumor center and invasive front of resected GC and compared their relationship with clinicopathological parameters and clinical outcomes." (PMID 34001012, 2021). "Besides, tumor size was evidently larger in the sh-RBPMS2 group in relation to the control group." (PMID 35137653, 2022). "However, the tumor size could be reduced by treatment with 5-aza-DC in sh-RBPMS2 group." (PMID 35137653, 2022). "The results displayed that the level of SCNN1B and RBPMS2 was significantly reduced while the expression of NFE2L3 and CLDN2 was increased in GC tumor tissues compared to paracarcinoma tissues." (PMID 35137653, 2022). "We found that RBPMS2 and DSC3 are prognostic biomarkers for tumor progression in progressive and de novo MIBC, respectively." (PMID 33731721, 2021). "Low expression of RBPMS2 protein in the tumor center was significantly correlated with the non-intestinal type and positive lymphatic invasion (P < 0.001 and P = 0.047)." (PMID 34001012, 2021). "High Noggin protein expression and EBV positivity at the invasive front were significantly correlated with better OS (P = 0.030 and P = 0.020), but not the high Noggin protein expression in tumor center lesions and RBPMS2 protein expression at the invasive front and tumor center." (PMID 34001012, 2021).
RBPMS2 also shares sentences with these, for which no sentence is quoted: gastro-intestinal stromal tumors (2 papers); breast carcinoma (1); coronary artery disease (1); episodic ataxia (1); esophageal cancer (1); hepatocellular carcinoma (1); liver disease (1); mastitis (1).